NEAT1 (nuclear paraspeckle assembly transcript 1)
Diseases named in the same sentence as NEAT1 in open-access papers (continued):
Sharing a sentence is not in itself a finding about the gene and the disease.
psoriasis (12 papers, 2020 to 2025). An autoimmune condition characterized by red, well-delineated plaques with silvery scales that are usually on the extensor surfaces and scalp. "Paeoniflorin controls the proliferation and migration of psoriasis HaCat cells through the NEAT1/miR-3194-5p/Galectin-7 axis." (PMID 40110044, 2025). "On the other hand, the lncRNA NEAT1 is expressed at low levels in the skin tissues of patients with psoriasis." (PMID 40725409, 2025). "The increased expression of nuclear paraspeckle assembly transcript 1 (NEAT1) in the skin cells of psoriasis patients affects the activity of transcription factors during epithelial differentiation." (PMID 39846685, 2025). "Screening of the expression of some common lncRNAs in psoriasis using real-time RT-PCR has shown decreased expression of the NEAT1 gene in lesional skin compared to healthy skin." (PMID 36901987, 2023). "Based on this observation, we decided to analyze NEAT1 expression in psoriasis and ichthyosis, two skin diseases characterized by keratinocytes hyper-proliferation and aberrant keratinization, respectively." (PMID 37365156, 2023). "Conversely, in psoriasis, a skin hyperproliferative disorders, we observed a marked reduction of NEAT1 levels." (PMID 37365156, 2023). "In contrast, NEAT1 (nuclear paraspeckle assembly transcript 1), PRINS (psoriasis susceptibility-related RNA gene induced by stress), and LINC00520 are examples of pathogenic lncRNAs, which promote disease progression." (PMID 35215236, 2022). "The upregulation of NEAT1 is reported to result in the targeted mediation of downstream miR-3194-5p to increase Galectin-7 expression, which subsequently inhibits the activity of psoriasis HaCat cells and exhibits therapeutic effects." (PMID 40725409, 2025). "Meanwhile, NEAT1 has been shown to be lowly regulated in psoriasis." (PMID 39337694, 2024). "In our psoriasis hypothesis, we assume NEAT1 to be down-regulated while MAP3K1-2 and AKAP13-AS1 are normally expressed." (PMID 39337694, 2024). "Several lncRNAs are upregulated in psoriasis, such as MSX2P1, XIST, FABP5P3, KLDHC7B-DT, or SPRR2C, whereas MEG3, GAS5, PRINS or NEAT1 are downregulated in psoriasis." (PMID 38256115, 2024). "Other upregulated lncRNA in psoriasis are MIR31HG, MSX2P1, XIST, FABP5P3, KLDHC7B-DT, or SPRR2C; whereas, MEG3, GAS5, PRINS or NEAT1 are downregulated in psoriasis." (PMID 37628670, 2023).
schizophrenia (12 papers, 2019 to 2026). A major psychotic disorder characterized by abnormalities in the perception or expression of reality. "NEAT1 has been shown to play a role in neuroinflammatory responses and immune signalling, which are implicated in conditions like depression and schizophrenia." (PMID 40038891, 2025). "The expression levels of lncRNA NEAT1 was reduced in the brain of patients with schizophrenia and loss of NEAT1 influenced multiple oligodendrocytes cell differentiation related genes that caused population of oligodendrocytes-lineage cells diminishment during brain development." (PMID 32514332, 2020). "However, when comparing data between sexes (males vs. females), GAS5, NEAT1 and OIP5‐AS1 expression levels had a higher and more significant association with schizophrenia in female patients compared to males." (PMID 35040588, 2022). "Furthermore, the association of FAS-AS1, GAS5, NEAT1, and OIP5-AS1 with schizophrenia differ between genders." (PMID 34366776, 2021). "Conversely, expression of NEAT1 is reduced in cortical brain regions from Schizophrenia patients." (PMID 34349622, 2021). "By evaluating lncRNAs in peripheral blood, it has been revealed that FAS-AS1, PVT1, TUG1, Neat1 and Neat2 were down-regulated, while THRIL was upregulated in schizophrenia compared with controls." (PMID 34366776, 2021). "Additionally, NEAT1–/– mice displayed a significant reduction in the numbers of oligodendrocyte-lineage cells and impaired expression of genes related to myelination, supporting a role for NEAT1 in oligodendrocyte function and related abnormalities in Schizophrenia pathology." (PMID 34349622, 2021). "MIAT, NEAT1, and MALAT1 are coordinately changed in schizophrenia." (PMID 36412908, 2022). "Recent studies have been carried out on OIP5‐AS1 along with other lncRNAs (FAS‐AS1, PVT1, TUG1, THRIL, NEAT1 and GAS5) due to their involvement in neurodevelopmental and/or neurobiological processes, and their involvement in signalling pathways present in patients with schizophrenia." (PMID 35040588, 2022). "Levels of GAS5, NEAT1 and OIP5‐AS1 were generally similar between patients diagnosed with schizophrenia and those negative for schizophrenia." (PMID 35040588, 2022).
acute kidney injury (11 papers, 2019 to 2025). Sudden and sustained deterioration of the kidney function characterized by decreased glomerular filtration rate, increased serum creatinine or oliguria. "LncRNA NEAT1 can play an important role in the pathogenesis of acute kidney injury by activating the NLRP3 inflammasome." (PMID 39973927, 2025). "Chen’s group indicated that NEAT1 was highly expressed in sepsis-induced acute kidney injury (AKI) patients." (PMID 32331347, 2020). "Nuclear-enriched abundant transcript 1 (Neat1) expression was observed to be elevated in acute kidney injury (AKI)." (PMID 32295041, 2020). "Previous studies showed that lncRNA NEAT1 promoted inflammatory responses and acute kidney injury." (PMID 35587223, 2022).
esophageal cancer (11 papers, 2016 to 2023). A primary or metastatic malignant neoplasm involving the esophagus. "Regardless, NEAT1 downregulation has been reported in invasive breast carcinoma, oesophageal cancer, pheochromocytoma, and paraganglioma, suggesting NEAT1 plays a tumour-suppressor role in these malignancies." (PMID 36139550, 2022). "The resulting signatures include genes that are highly related to cancer, such as H19 and NEAT1, which possess perfect prognostic values for esophageal cancer and HNSCC, respectively." (PMID 32024523, 2020). "Consistently, NEAT1 exerted a relative high level in esophageal cancer cells." (PMID 33680941, 2020). "In esophageal carcinoma (ESCA) and thymoma (THYM), NEAT1 expression was also decreased but without statistical significance." (PMID 31186635, 2019).
multiple endocrine neoplasia (11 papers, 2018 to 2025). Multiple endocrine neoplasia (MEN) is a group of rare inherited cancer syndromes characterized by the development of two or more endocrine gland tumors, sometimes with tumor development in other tissues or organs. "NEAT1, a lincRNA extensively investigated in the domain of cancer pathologies, is synthesised from the multiple endocrine neoplasia (MEN) site located on chromosome 11q13.1." (PMID 40387409, 2025). "LncRNA Nuclear paraspeckle assembly transcript 1 (Neat1), transcribed from the multiple endocrine neoplasia (Men) locus, is an important regulator of immune responses." (PMID 37716986, 2023). "Nuclear paraspeckles assembly transcript 1 (NEAT1) is a lncRNA transcribed from the multiple endocrine neoplasia locus located on human chromosome 11." (PMID 32283739, 2020). "Nuclear enriched abundant transcript 1 (NEAT1) is a lncRNAtranscribed from the multiple endocrine neoplasia locus." (PMID 32453338, 2020). "In the current study, we examine lncRNAs that associate with NLRP3 inflammasome in mouse macrophages and identify Neat1 (nuclear enriched abundant transcript 1), a lncRNA transcribed from the multiple endocrine neoplasia locus (hence also known as Men)." (PMID 30940803, 2019). "NEAT1, nuclear enriched abundant transcript 1, is a novel lncRNA, transcribed from multiple endocrine neoplasia locus." (PMID 31462890, 2019). "An lncRNA termed nuclear paraspeckle assembly transcript 1 (NEAT1), which was first identified in patients with multiple endocrine neoplasia and is located on chromosome 11q13.1, is an important component of nuclear paraspeckles." (PMID 29515109, 2018). "LncRNA Nuclear Enriched Abundant Transcript 1 (NEAT1), also named as Nuclear Paraspeckle Assembly Transcript 1, is transcribed from the multiple endocrine neoplasia locus on chromosome 11, and it is confirmed to play a crucial role in the structure of paraspeckles." (PMID 29416703, 2018). "Nuclear paraspeckle assembly transcript 1 (NEAT1) is an lncRNA transcribed from the familial tumor syndrome multiple endocrine neoplasia (MEN)." (PMID 38002304, 2023). "One well-known lncRNA, NEAT1, is transcribed from the tumor syndrome multiple endocrine neoplasia (MEN) family type 1 locus on chromosome 11q13.1." (PMID 31290116, 2019). "Nuclear paraspeckle assembly transcript 1 (NEAT1), which is transcribed from the multiple endocrine neoplasia (MEN) locus on chromosome 11q13.1, is a well-studied lincRNA in the field of cancer diseases." (PMID 36011001, 2022).
acute myeloid leukemia (10 papers, 2020 to 2025). Acute myeloid leukemia (AML) is a group of neoplasms arising from precursor cells committed to the myeloid cell-line differentiation. "In patients with acute myeloid leukemia, NEAT1 is downregulated and subsequently decreases the expression of CREBRF, promoting the progression of the disease." (PMID 36011001, 2022). "NEAT1 upregulation suppresses cell growth, migration, and invasion but enhances the apoptosis of acute myeloid leukemia cells." (PMID 36011001, 2022). "Herein, an adverse effect of NEAT1 is reported, showing that the short isoform, NEAT1_1 suppresses acute myeloid leukemia (AML) development." (PMID 34609794, 2021). "In this section, we summarize and discuss the role of the NEAT1/miRNA/target axis in circulatory system tumors, including hemangioma, acute myeloid leukemia, T-cell acute lymphoblastic leukemia, diffuse large B-cell lymphoma, Hodgkin's lymphoma, and multiple myeloma." (PMID 34512157, 2021). "Interestingly, NEAT1 exerts an opposite function in acute myeloid leukemia." (PMID 36011001, 2022). "However, NEAT1 overexpression seems to be a protective factor in acute myeloid leukemia (AML), and lower NEAT1 levels are responsible for differentiation disorders in AML." (PMID 36011001, 2022). "However, this work reveals that NEAT1 functions as a tumor suppressor in acute myeloid leukemia (AML) by translocating to cytoplasm in AML cells, and manipulating Wnt signaling." (PMID 34609794, 2021). "Furthermore, NEAT1 translocated from the nucleus to the cytoplasm interacts with E3 ubiquitin ligase to promote DVL2 degradation, acting as a tumor suppressor in acute myeloid leukemia." (PMID 41268533, 2025).
epilepsy (10 papers, 2017 to 2026). A brain disorder characterized by episodes of abnormally increased neuronal discharge resulting in transient episodes of sensory or motor neurological dysfunction, or psychic dysfunction. "This study provides novel insights into the epigenetic regulation of TSC‐associated epilepsy, demonstrating that NEAT1 contributes to both mTORC1‐ and mTORC2‐dependent mechanisms." (PMID 41090516, 2026). "These efforts are essential to establish NEAT1 as a viable therapeutic target in the evolving treatment paradigm of TSC‐associated epilepsy." (PMID 41090516, 2026). "However, we found different induction kinetic in two other primate-specific lncRNAs dependent on electrical activity, LINCAK023739 and LINCBC028229, and for NEAT1, associated with epilepsy." (PMID 38941065, 2025). "This study provides new insights into the transcriptional regulation of TSC‐related epilepsy, highlighting the therapeutic potential of NEAT1." (PMID 41090516, 2026). "Investigating the role of the epigenetic long non‐coding RNA NEAT1 in TSC‐related epilepsy and cognition is essential." (PMID 41090516, 2026). "This highlights the role of NEAT1 in the electrophysiological and molecular mechanisms underlying TSC‐related epilepsy." (PMID 41090516, 2026). "Future research should further investigate NEAT1's therapeutic potential and its role in stratifying epilepsy phenotypes for personalized treatment approaches." (PMID 41090516, 2026). "NEAT1 is differentially expressed in TSC‐related epilepsy and influences neuronal excitability by regulating the PI3K/AKT/mTOR signaling pathway." (PMID 41090516, 2026). "These insights enhance the understanding of mTOR pathway involvement in TSC‐related epilepsy and underscore the potential of targeting mTORC1, as well as epigenetic factors like NEAT1, for more effective therapeutic strategies." (PMID 41090516, 2026). "These coordinated actions position NEAT1 as a promising therapeutic target for epilepsy, given its dual regulatory capacity over glial functions (myelination regulation, phenotypic polarization) and inflammatory network modulation." (PMID 40791576, 2025). "Studies have found that NEAT1 is significantly elevated in the cerebral cortex of epilepsy patients, particularly in high-activity areas." (PMID 39976094, 2025). "Further research has revealed that lncRNA NEAT1 can affect the inflammatory response and cell vitality in epilepsy by targeting miRNA-129-5p and further regulating the Notch signaling pathway." (PMID 39976094, 2025). "In particular, they found the expression level of NEAT1 was markedly increased in the hippocampal neurons of epilepsy patients." (PMID 35328484, 2022). "Our results indicate a role for NEAT1 in modulating human neuronal activity and suggest a novel mechanistic link between an activity-dependent long non-coding RNA and epilepsy." (PMID 28054653, 2017). "Using human epilepsy patient samples and in vivo rat seizure models, we show that excessive excitability results in chronic insensitivity of NEAT1 to neuronal activation." (PMID 28054653, 2017). "In the context of TSC‐related epilepsy, low NEAT1 expression appears to mitigate seizure activity, suggesting that NEAT1 may contribute to epilepsy pathogenesis by disrupting neurotransmitter receptor balance to modulate seizure activity." (PMID 41090516, 2026). "However, in the pilocarpine-induced epilepsy model, NEAT1 is briefly reduced during the acute phase of epilepsy." (PMID 39976094, 2025). "NEAT1 also has the ability to regulate neuronal excitability by interacting with ion channel regulatory proteins, such as potassium channel-interacting proteins KCNAB2 and KCNIP1, which are associated with epilepsy and neuronal excitability." (PMID 39976094, 2025).
epilepsy (continued). "Additionally, it was found that lncRNA NEAT1 affects inflammatory response via regulating Notch signaling pathway in epilepsy cell model." (PMID 35603469, 2022). "Furthermore, they investigated the role of NEAT1 in epilepsy, as well as examined the function of the miR-129-5p and Notch signaling pathways in an epilepsy model in vitro." (PMID 35328484, 2022). "The nuclear paraspeckle assembly transcript 1 (NEAT1) has been demonstrated to regulate both neural activity and inflammation though interacting with mTOR pathway in epilepsy." (PMID 35898503, 2022). "Meanwhile, NEAT1 promotes IL-6, cyclooxygenase (COX)-2, and TNF-α expression by targeting miR-129-5p and activating the Notch signaling pathway in epilepsy." (PMID 35898503, 2022). "It has been known that NEAT1 is a competitive endogenous RNA, and it was closely related to T2DM, neurodegenerative diseases, epilepsy, and other mental illnesses." (PMID 30733823, 2019). "Targeting NEAT1 with antisense oligonucleotides or siRNAs, in combination with established mTOR inhibitors such as everolimus, represents a promising dual‐approach strategy for the treatment of TSC‐related epilepsy." (PMID 41090516, 2026).
autoimmune disease (9 papers, 2017 to 2025). A disorder resulting from loss of function or tissue destruction of an organ or multiple organs, arising from humoral or cellular immune responses of the individual to their own tissue constituents. "The role of Neat1 in driving pathogenic Th17 cell responses and autoimmunity identifies Neat1 as a promising therapeutic target in uveitis and other Th17 cell-mediated autoimmune diseases." (PMID 37716986, 2023). "In our study, a significant association was found between NEAT1 expression in families with a positive history of the disease, such that NEAT1 expression was increased in individuals with a family background of autoimmune disease." (PMID 35266286, 2022). "Intriguingly, long non-coding RNAs (lncRNAs), such as nuclear enriched abundant transcript 1 (NEAT1), are increasingly recognized as epigenetic regulators in autoimmune diseases." (PMID 41457558, 2025). "Our findings elucidate a previously unrecognized mechanistic insight into the action of Neat1 in promoting antigen-specific Th17 responses and autoimmunity, and may facilitate the development of therapeutic targets for T cell-mediated autoimmune diseases." (PMID 37716986, 2023). "Because of its role(s) in immune response, it has been suggested that NEAT1 could be used as a therapeutic target for inflammatory and autoimmune diseases." (PMID 35127819, 2021). "We selected NEAT1 and KCNQ1OT1 as the lncRNAs with the most interactions with microRNAs in autoimmune diseases and the Th17 differentiation pathway." (PMID 35266286, 2022).
diabetic retinopathy (9 papers, 2021 to 2025). "The knockdown of NEAT1 will reduce glucose-induced damage to the mitochondrial membrane and DNA, suggesting that NEAT1 protects mitochondrial homeostasis and reduces the formation of degenerative capillaries in diabetic retinopathy." (PMID 40362651, 2025). "Knockdown of the lncRNA NEAT1 exerts suppressive effects on diabetic retinopathy progression." (PMID 34707685, 2021). "Numerous lncRNA have been linked to oxidative damage in diabetic retinopathy, including metastasis-associated lung adenocarcinoma transcript 1 (MALAT1), Hox antisense intergenic RNA (HOTAIR), nuclear paraspeckle assembly transcript 1 (NEAT1), Arid2-IR, OGRU, and HIF1 antisense RNA 2 (HIF1A-AS2)." (PMID 37627644, 2023).
ischemia (9 papers, 2020 to 2024). A hypoperfusion of the BLOOD through an organ or tissue caused by a PATHOLOGIC CONSTRICTION or obstruction of its BLOOD VESSELS, or an absence of BLOOD CIRCULATION. "However, the potential roles and underlying molecular mechanisms of NEAT1 in cerebral ischaemia/reperfusion (I/R) injury remain unclear." (PMID 33184298, 2020). "For example, Neat1, a ubiquitously expressed lncRNA, is increased in astrocytes in response to ischemia and AD models." (PMID 39207536, 2024). "Upon induction of stroke, mice displayed a temporal profile of NEAT1 expression within the ischemic tissue, with a peak at 1 day post-ischemia (dpi)." (PMID 38212456, 2024). "However, other lncRNAs, such as Meg3, Malat1, GAS5, NEAT1, and LOC105374325 mediated the renal cell apoptosis caused by ischemia." (PMID 36552750, 2022). "Furthermore, NEAT1 has been proven as a regulator in myocardial apoptosis and autophagy which results in aggravated myocardial ischemia reperfusion (I/R) injury in diabetic rats, however, the roles of NEAT1 in CHD-related MI remains elusive." (PMID 34081624, 2021). "Notably, suppression of NEAT1 also blunts myocardial ischemia reperfusion injury by abrogating apoptosis in diabetic rats." (PMID 32089649, 2020).